TNF (tumor necrosis factor)
Diseases named in the same sentence as TNF in open-access papers (continued):
Sharing a sentence is not in itself a finding about the gene and the disease.
rheumatoid arthritis (continued). "It has been demonstrated that osteocytes are implicated in inflammatory diseases such as rheumatoid arthritis and may produce interleukin (IL)-1β, IL-6, and tumor necrosis factor-α (TNF-α) to mediate bone destruction in rheumatoid arthritis pathogenesis." (PMID 34093433, 2021). "Finally, our findings have the potential to inform patient stratification in other immune-mediated inflammatory diseases such as inflammatory bowel disease and rheumatoid arthritis where TNF-blockade is also a therapeutic cornerstone." (PMID 34362923, 2021). "In addition, we demonstrated SKN suppressed the migration and invasion of TNF-α-induced FLS from rheumatoid arthritis patient." (PMID 34600581, 2021). "Tumor necrosis factor alpha mediates the inflammatory response;53 hence, agents that block TNFα activity are widely used to treat inflammatory diseases and certain autoimmune diseases (such as rheumatoid arthritis)." (PMID 34117371, 2021). "Anti-TNF therapeutics are approved for the treatment of rheumatoid arthritis." (PMID 34305946, 2021). "In addition, substantial amounts of inflammatory cytokines (INF-γ, IL-17, and TNF-α) from CD4+ T-cells were abundantly augmented due to upregulated expression of calcium-release-activated calcium channels in patients with rheumatoid arthritis." (PMID 34639190, 2021). "Similarly, another study from the British Society for Rheumatology Biologics Register for Rheumatoid Arthritis reported a crude IR for OIs (excluding tuberculosis) of 0.13 for all bDMARDs and TNF inhibitors, 0.15 for rituximab and 0.08 for tocilizumab." (PMID 33430948, 2021). "In addition, it can also be used as a revised strategy in other TNF-mediated diseases, that is, rheumatoid arthritis, inflammatory bowel disease, and psoriasis." (PMID 34804701, 2021). "In rheumatoid arthritis (RA), an inflammatory disease of the joints in which bone loss is observed, SOST inhibition promotes TNFα-mediated tissue damage, demonstrating a possible protective role of SOST in TNFα-mediated chronic inflammation." (PMID 34502021, 2021). "Etanercept (an anti-TNF-α antibody), beneficial in the treatment of rheumatoid arthritis, might be beneficial in baboons undergoing pig organ transplantation if administered on the day of operation or on the previous day." (PMID 34956220, 2021). "A revolution in the treatment of rheumatoid arthritis occurred when drugs aimed at inhibiting pro-inflammatory cytokines were introduced, especially those targeting tumor necrosis factor alpha (TNF-α), which is involved in most of the studied inflammatory processes." (PMID 33498456, 2021). "Clinical reduction of serum levels of TNF-α and clinical disease activity scores in rheumatoid arthritis and C-reactive protein (CRP) in Crohn's disease have been reported, in response to invasive VNS-devices, which necessitates operative implantation with potential postoperative complications." (PMID 34135691, 2021). "TNF levels in serum and synovial fluid of rheumatoid arthritis patients vary considerably." (PMID 33495445, 2021). "The treatment of rheumatoid arthritis (RA) has greatly progressed with the use of new biological agents including tumor necrosis factor (TNF) inhibitors, which have been observed to be efficacious for RA when administered in combination with the chemotherapy agent methotrexate (MTX)." (PMID 33968956, 2021). "The role of TNF-α is widely characterized in the pathogenesis of rheumatoid arthritis (RA)." (PMID 33897688, 2021). "TNF-α is a strong pro-inflammatory cytokine that is important for rheumatoid arthritis." (PMID 34209109, 2021). "Furthermore, inhibition of the production of pro-inflammatory mediators including TNF-α and IL-6 by pseurotin A was observed in the synovial fluid of rats with rheumatoid arthritis." (PMID 33669259, 2021). "Besides, pathways affecting the immune system, including IL-17 signaling, TNF signaling, as well as rheumatoid arthritis, were enriched." (PMID 33509158, 2021).
rheumatoid arthritis (continued). "In rheumatoid arthritis, steroid and anti-TNF therapy induce an increase IgG sialylation." (PMID 33897440, 2021). "Additionally, n-3 PUFAs decrease tumor necrosis factor α (TNF-α) which is involved in bone destruction in rheumatoid arthritis and can also reduce the secretion of prostaglandin E2 (a potent stimulator of bone resorption)." (PMID 34578973, 2021). "This hypothesis is supported by accumulation of ICR expressing T cells during chronic inflammatory diseases such as Crohn’s, ulcerative colitis and rheumatoid arthritis, mainly maintained by TNF-α, IFN-γ, and IL-6, that are also seen in CL lesions." (PMID 33767700, 2021). "The hTNFtg mouse model is a well-established arthritis model in which a constitutive overexpression of TNFα is sufficient to induce a spontaneous chronic and severe rheumatoid arthritis phenotype, characterized by synovial inflammation and pannus formation, cartilage damage, and bone destruction." (PMID 34239010, 2021). "Mice with human TNF overexpression (hTNF Tg mice with a high transgene copy number and dysregulated control) start to develop severe polyarthritis as early as 3-4 weeks after birth with similar characteristics observed in rheumatoid arthritis patients." (PMID 34054827, 2021). "Similar results have been reported for tumor necrosis factor-α (TNF-α) which promoted platelet aggregation and activation, while TNF-α inhibitors abrogated platelet activation, platelet-leukocyte interactions, and tissue factor expression in patients with rheumatoid arthritis." (PMID 34681830, 2021). "TNF inhibitor increased serum PTH level in patients with rheumatoid arthritis." (PMID 33861790, 2021). "Genes in module one were significantly enriched in TNF signaling pathway and rheumatoid arthritis." (PMID 34054546, 2021). "With respect to pathway enrichment, KEGG pathway analysis showed that the candidate DEGs were mainly enriched in the TNF signaling pathway, rheumatoid arthritis, osteoclast differentiation, interleukin-17 signaling pathway, and mitogen-activated protein kinase signaling pathway." (PMID 34670585, 2021). "For example, patients with Rheumatoid Arthritis (RA) and Systemic Lupus Erythematosus (SLE) show an increased insulin resistance (IR), which is linked to the systemic inflammation induced by certain inflammatory cytokines (TNF-α and IL-6)." (PMID 34372196, 2021). "They concluded that the use of TNF alpha-blockers in ankylosing spondylitis and psoriatic arthritis, not in rheumatoid arthritis, was associated with developing demyelinating disorders." (PMID 34804701, 2021). "Moreover, there is a close association between disseminated histoplasmosis and the use of tumor necrosis factor (TNF) inhibitors in rheumatoid arthritis (RA)." (PMID 34277293, 2021). "However, 1 year of anti-TNF-α therapy showed beneficial effects on vascular function in rheumatoid arthritis and ankylosing spondylitis patients." (PMID 34300351, 2021). "Additionally, both NO and TNF-α have important roles in progressive osteoarthritis and rheumatoid arthritis." (PMID 33763143, 2021). "The most potent TNF-α–specific inhibitors (TNFIs) approved by the food and drug administration are biologic drugs, which are used for treatment of peripheral inflammatory conditions, including rheumatoid arthritis, Crohn disease, and psoriasis." (PMID 33434745, 2021). "Moreover, long-term VN stimulation using an implanted VNS-device reduced disease activity and inhibited production of TNF-α in patients with rheumatoid arthritis, suggesting treatment efficacy of t-VNS in similar autoimmune and inflammatory diseases." (PMID 34135691, 2021). "Alternatively, TNFI may restore Th1 responses and IFN-γ expression by counteracting the side effects of chronic TNF exposure as described for rheumatoid arthritis, ankylosing spondylitis or moderate psoriasis." (PMID 34093562, 2021).
rheumatoid arthritis (continued). "Increased production of TNF-α may trigger excessive osteoclastic bone resorption and promote the development of inflammatory bone diseases, such as rheumatoid arthritis and periodontal disease." (PMID 34610045, 2021). "Targeting TNF-α increases mature blood vessels in rheumatoid arthritis synovium." (PMID 33966638, 2021). "The original discovery that ABCF1 expression was regulated by TNF-α stimulation suggested a link to immune responses, although no differential expression patterns were observed for synoviocytes from healthy individuals or those with rheumatoid arthritis." (PMID 33042865, 2020). "Thus, TNF-α has been widely accepted as an attractive target for biologic drugs against rheumatoid arthritis and other autoimmune diseases." (PMID 32880389, 2020). "TNF-α is a central risk factor in the pathogenesis of these diseases, and treatment of rheumatoid arthritis with the anti-TNF-α antibody infliximab improves the number and functional properties of EPCs11,24, indicating a close relationship between TNF-α and EPC dysfunction." (PMID 32770080, 2020). "Furthermore, multiple observational studies have shown that TNF inhibition reduces atherosclerosis and cardiovascular events when administered to patients with rheumatoid arthritis." (PMID 32805626, 2020). "Based on accumulating knowledge that some inflammatory cytokines, such as tumor necrosis factor α (TNFα), IL-1, and IL-6, play critical roles in the onset and progression of rheumatoid arthritis, specific inhibitory reagents for these cytokines have been developed." (PMID 32079226, 2020). "RANKL, a member of the Tumor Necrosis Factor (TNF) superfamily, promotes osteoclast differentiation, activity, and survival, and is implicated in the bone and joint destruction characteristic of rheumatoid arthritis." (PMID 32517792, 2020). "For example, in the clinic, TNFα inhibitors are used with relatively high success in therapy of autoimmune diseases and inflammatory disorders, and therapies directed to IL-6 are used in rheumatoid arthritis." (PMID 33585241, 2020). "Moreover, another study showed that blocking of TNF-α markedly reduced the levels of IL-6, IL-1β, and IL-17 in patients with rheumatoid arthritis, indicating that Th17 cell differentiation is promoted by TNF-α through IL-6 and IL-1β." (PMID 33204736, 2020). "Tumor necrosis factor (TNF)-alpha, a pro-inflammatory cytokine, has a crucial role in the pathogenesis of chronic inflammatory and immune-mediated diseases such as rheumatoid arthritis, ankylosing spondylitis, Crohn’s disease, ulcerative colitis, psoriasis and psoriatic arthritis." (PMID 33414791, 2020). "Several epidemiological, as well as clinical studies, show that androgens attenuate the expression of inflammatory biomarkers including TNF-α, IL-1β, and IL-6 in various chronic inflammatory diseases like Crohn’s disease, psoriasis, rheumatoid arthritis and allergic asthma." (PMID 32120970, 2020). "As TNFα, IL-1, and IL-6 affect chondrocytes during rheumatoid arthritis development, their intracellular signaling pathways, including NF-ĸB and JAK/signal transducer and activator of transcription (STAT) signaling cascades, play a central role in destruction of cartilage tissues." (PMID 32079226, 2020). "Based on the recognized role of TNF in autoimmune disorders, since 1988 different drugs targeting TNF signaling have been successfully introduced for the treatment of inflammatory disease such as rheumatoid arthritis, inflammatory bowel disease, Crohn’s disease and ankylosing spondylitis, psoriasis." (PMID 33066433, 2020). "For example, in the field of autoimmune disease, mAbs such as Infliximab (Remicade®; Janssen Biotech) or Adalimumab (Humira®; Abbott), work directly against the pro-inflammatory cytokine, tumor necrosis factor α (TNF-α) to treat severe rheumatoid arthritis (RA)." (PMID 32586313, 2020).
rheumatoid arthritis (continued). "We present a case of a 60-year-old male with a history of psoriatic and rheumatoid arthritis treated with a tumor necrosis factor inhibitor (adalimumab), who presented with abdominal pain and was found to have gastrointestinal histoplasmosis as an obstructing ileocecal mass." (PMID 33510984, 2020). "Although monoclonal antibody therapies have been successfully introduced for the treatment of certain disorders (such as anti-TNF for rheumatoid arthritis), glucocorticoids remain the first-in-line option for many other chronic diseases including asthma, multiple sclerosis, and multiple myeloma." (PMID 33071974, 2020). "A small placebo-controlled clinical trial investigating the effect of a 24-week therapy with etanercept, an anti-TNF agent used to treat rheumatoid arthritis, in children newly diagnosed with T1D reported an increase in C-peptide and a decrease in HbA1c in the etanercept group." (PMID 32967650, 2020). "Noteworthy, anti-TNF-α therapy in elderly rheumatoid arthritis patients might exacerbate heart failure and reduce survival." (PMID 33053859, 2020). "In patients with rheumatoid arthritis, methotrexate and anti-TNF drugs were associated with an increased risk of nonmelanoma skin cancer." (PMID 32188490, 2020). "Clinical data have demonstrated the therapeutic effects of anti-TNF-α therapies against autoimmune diseases, including rheumatoid arthritis, juvenile rheumatoid arthritis, inflammatory bowel disease (IBD), ankylosing spondylitis, psoriasis, and psoriatic arthritis." (PMID 33003495, 2020). "Based on a number of laboratory data and clinical evidence, TNF-α inhibitors were implied as new therapeutic strategies in several immune-related diseases, including rheumatoid arthritis, asthma, sarcoidosis, inflammatory bowel disease, pancreatitis, and so on." (PMID 32787816, 2020). "Similar to our findings, results from several case reports and cohort studies have described meningitis or meningoencephalitis in patients with autoimmune disease (rheumatoid arthritis, ankylosing spondylitis, psoriasis and psoriatic arthritis, Crohn disease) treated with a TNF inhibitor." (PMID 32421186, 2020). "TNF‐α is a central mediator of inflammation and plays an important role in the host response to injury, but overexpression of TNF‐a can result in severe tissue damage and underlies a number of disease states, such as rheumatoid arthritis, ARDS and malignancy." (PMID 32735065, 2020). "Besides, TNFR2 upregulation in rat and human BM-MSCs effectively increased their therapeutic potential in cardiac ischemia and inflammatory disorders like rheumatoid arthritis (RA), which was accompanied by decreased IL-6, IL-1β, and TNFα secretion." (PMID 33344453, 2020). "Anti-TNF-α treatment is most commonly used to treat rheumatoid arthritis." (PMID 33053859, 2020). "In systemic sclerosis and rheumatoid arthritis, DPTs secrete mainly interleukin-4, whereas in tumors, such as melanoma and cutaneous lymphoma, the primary cytokine produced is tumor necrosis factor (TNF)-α." (PMID 31612695, 2020). "Indeed, inhibitory reagents for IL-1, IL-6, and TNFα provide clinical benefits for rheumatoid arthritis patients." (PMID 32079226, 2020). "However, in 1995, a chimeric antibody against TNFα (infliximab) was found to have a remarkable therapeutic effect on rheumatoid arthritis." (PMID 32743515, 2020). "Rheumatoid arthritis and TNF signaling pathways are related to the inflammatory reaction process." (PMID 32215271, 2020). "This strategy has been integrated into the treatment of rheumatoid arthritis with high success as well: notably Tocilizumab (Target: IL-6R), Adalimumab (Target: TNFα) and Goliumab (Target: TNFα) are approved and highly successful therapeutics as mono- or combination therapy with DMARDs." (PMID 32082321, 2020). "Moreover, anti-IL-6 therapies have proven especially useful for example in treating rheumatoid arthritis in patients unresponsive to TNF inhibitors." (PMID 32411011, 2020).
rheumatoid arthritis (continued). "Furthermore, the KEGG pathway analysis revealed that the common DEGs were particularly enriched in cytokine-cytokine receptor interaction, TNF signaling pathway, chemokine signaling pathway, pertussis, and rheumatoid arthritis." (PMID 33144895, 2020). "Moreover, it has been reported in rheumatoid arthritis synovial macrophages that the late (chronic) phase of TNFα signaling is characterized by the expression of some genes not induced during the early and acute pro-inflammatory phase." (PMID 32516132, 2020). "Importantly, in rheumatoid arthritis, anti-TNF-α therapy protects from the development of ischemic cardiac events, but it shows no cardioprotective effects in the post-ischemic heart." (PMID 33053859, 2020). "TNFα antagonists exert their immunosuppressive effects by direct suppression of TNFα which plays a central role in rheumatoid arthritis through the activation of cytokine and chemokine production, elevated expression of endothelial-cell adhesion molecules and promotion of angiogenesis." (PMID 31186464, 2019). "The improved anti-inflammatory activity of the synbiotic may be due to the combinatory use of acacia gum, and the TNF-α-level-lowering effect of acacia gum make it significant in patients with Crohn’s disease and rheumatoid arthritis." (PMID 31817751, 2019). "Interesting, the top 4 enriched pathways were significantly relevant to Immune reaction, including cytokine-cytokine receptor interaction (P = 4.61 × 10−13), rheumatoid arthritis (P = 1.90 × 10−6), chemokine signaling pathway (P = 1.01 × 10−5) and TNF signaling pathway (P = 2.79 × 10−4)." (PMID 31371761, 2019). "One option to attenuate TNF-α is to use an antibody approach to inhibit and clear TNF-α before it could reach its target; this has effectively been achieved in the treatment of rheumatoid arthritis." (PMID 30682785, 2019). "Treatment of rheumatoid arthritis with anti-TNFα (tumor necrosis factor-alpha) agents may lead to autoantibody formation and flares of vasculitis." (PMID 31632872, 2019). "During treatment of rheumatoid arthritis, systemic administration of anti-TNFα antibodies may induce on-target toxicities, limiting their application." (PMID 31194726, 2019). "Also, RF positivity, SJC-28, TJC-28, CRP, erythrocyte sedimentation rate (ESR), uncarboxylated osteocalcin (ucOC), MMP-3, TNF-α, IL-6, disease Activity Score-28 for Rheumatoid Arthritis with ESR (DAS28-ESR) levels were alleviated." (PMID 31013659, 2019). "The KEGG pathway analysis results showed that up-DEGs were enriched in proteoglycans in cytokine-cytokine receptor interaction, chemokine signaling pathway, rheumatoid arthritis, and TNF signaling pathway, whereas down-DEGs were enriched in the PPAR signaling pathway and AMPK signaling pathway." (PMID 31139654, 2019). "It was reported that leflunomide combined with TNF-α inhibitors could effectively improve rheumatoid arthritis." (PMID 31552773, 2019). "With the concept of TNF-α as the tip of pro-inflammatory network in early Rheumatoid Arthritis (RA) pathogenesis, anti-TNF-α antibodies (e.g., infliximab, etanercept, and adalimumab) were developed as prescription drugs for the treatment of rheumatoid arthritis by neutralizing TNF-α." (PMID 30691120, 2019). "An example is etanercept, a TNF antibody used to treat rheumatoid arthritis." (PMID 30947238, 2019). "In addition, VNS significantly inhibited TNF production in a whole blood assay for up to 84 days, and positively affected disease severity in a pilot study with rheumatoid arthritis patients." (PMID 30862827, 2019). "Despite the efficacy of anti-TNF drugs for treatment of rheumatoid arthritis, Crohn’s disease and psoriasis, these drugs block the action of both tmTNF-α and sTNF-α and thus can increase the risk of infection, malignancy and development of secondary autoimmune diseases." (PMID 31383857, 2019). "Moxibustion could regulate serum TNF-α level and reduce foot swelling in rats with rheumatoid arthritis." (PMID 31616260, 2019).